BMP10 (bone morphogenetic protein 10)
Description:
Required for maintaining the proliferative activity of embryonic cardiomyocytes by preventing premature activation of the negative cell cycle regulator CDKN1C/p57KIP and maintaining the required expression levels of cardiogenic factors such as MEF2C and NKX2-5. Acts as a ligand for ACVRL1/ALK1, BMPR1A/ALK3 and BMPR1B/ALK6, leading to activation of SMAD1, SMAD5 and SMAD8 transcription factors. Inhibits endothelial cell migration and growth. May reduce cell migration and cell matrix adhesion in breast cancer cell lines.
Tractability: Antibody: its Gene Ontology location is reachable by antibodies, with high confidence; UniProt places it where antibodies can reach, with medium confidence; UniProt predicts a signal peptide or a membrane-spanning region. Other modalities: a drug acting on it is in phase 2 or 3 trials.
Target class: Enzyme; Metallo protease M12A subfamily; Metallo protease; Protease; Metallo protease MAM clan
Gene: Protein-coding gene on chromosome 2 (68,860,909 to 68,871,397, reverse strand). Ensembl gene ENSG00000163217.
Subcellular location: Secreted
Pathways (Reactome):
Extracellular matrix organization: Molecules associated with elastic fibres
Signal Transduction: Signaling by BMP
Gene Ontology:
Molecular function: growth factor activity; hormone activity; protein binding; receptor serine/threonine kinase binding; telethonin binding; cytokine activity
Biological process: activin receptor signaling pathway; BMP signaling pathway; negative regulation of cell growth; negative regulation of cell migration; negative regulation of endothelial cell migration; positive regulation of cardiac muscle hypertrophy; positive regulation of DNA-templated transcription; positive regulation of sarcomere organization; positive regulation of SMAD protein signal transduction; regulation of cardiac muscle contraction; regulation of cardiac muscle hypertrophy in response to stress; adult heart development; atrial cardiac muscle tissue morphogenesis; cardiac muscle cell proliferation; heart trabecula formation; negative regulation of cardiac muscle hypertrophy; positive regulation of cardiac muscle cell proliferation; positive regulation of cell proliferation involved in heart morphogenesis; sarcomere organization; ventricular cardiac muscle cell development; ventricular cardiac muscle tissue morphogenesis; positive regulation of cartilage development; positive regulation of multicellular organismal process; regulation of cardiac muscle hypertrophy; regulation of transmembrane receptor protein serine/threonine kinase signaling pathway
Cellular component: cell surface; cytoplasm; extracellular region; Z disc
Genetic constraint (gnomAD): Loss-of-function variants: 9 observed, 31.25 expected, observed/expected ratio (o/e) 0.29, 90% interval 0.17 to 0.5. The upper end of that interval is the gene's LOEUF score, 0.5, which puts it in group 2 of 6, group 1 being the genes least tolerant of losing a copy. Missense variants: 474 observed, 552.53 expected, observed/expected ratio (o/e) 0.86, 90% interval 0.8 to 0.93. Synonymous variants: 202 observed, 211.14 expected, observed/expected ratio (o/e) 0.96, 90% interval 0.85 to 1.08.
Gene-disease validity (ClinGen):
ClinGen rates the evidence that BMP10 causes each of these diseases.
congenital heart disease (autosomal dominant): Limited. A heart disease that is present at birth.
pulmonary arterial hypertension (autosomal dominant): Limited. Pulmonary arterial hypertension (PAH) is a group of diseases characterized by mean pulmonary artery pressure >20 mmHg and elevated pulmonary arterial resistance leading to right heart failure.
Homologues: Orthologues: chimpanzee BMP10 (99% identical), macaque BMP10 (98% identical), dog BMP10 (92% identical), guinea pig BMP10 (90% identical), pig BMP10 (90% identical), rat Bmp10 (85% identical), mouse Bmp10 (85% identical), rabbit BMP10 (79% identical), tropical clawed frog bmp10 (61% identical), zebrafish bmp10 (55% identical), zebrafish bmp10l (39% identical). Paralogues in human: GDF2 (39% identical), BMP2 (30% identical), GDF6 (29% identical), BMP4 (29% identical), GDF7 (26% identical), BMP6 (25% identical), GDF5 (25% identical), BMP5 (25% identical), BMP7 (25% identical), BMP8B (24% identical), BMP8A (23% identical), MSTN (21% identical), and 19 more.
Diseases named in the same sentence as BMP10 in open-access papers:
BMP10 is named in the same sentence as 57 diseases in open-access papers, as found by Europe PMC text mining. Sharing a sentence is not in itself a finding about the gene and the disease. The quoted sentences say what the papers report.
pulmonary hypertension (9 papers, 2023 to 2025). Increased pressure within the pulmonary circulation due to lung or heart disorder. "BMP10 is currently viewed as one of the major molecules playing a critical role in pulmonary hypertension, which is a common complication of COPD." (PMID 37083575, 2023). "Also administration of the ligand trap ALK1‐ECD, which inhibits both BMP9 and BMP10, blunted the pulmonary hypertension in the rat MCT and SuHx models." (PMID 35434863, 2023). "BMP9 or BMP10 is a the cognate ligand that binds to ALK1 and this pathway is important for a wide range of diseases from pulmonary hypertension to cancer." (PMID 39196046, 2023).
hereditary hemorrhagic telangiectasia (8 papers, 2013 to 2025). A disorder of angiogenesis leading to arteriovenous dilatations: cutaneo-mucosal hemorrhagic telangiectasias and visceral shunting. "Mutations in ALK1 (ACVRL1), the receptor for BMP9/BMP10, are linked to severe liver vascular malformations in hereditary hemorrhagic telangiectasia (HHT)." (PMID 40260391, 2025). "In arteriovenous malformation caused by hereditary hemorrhagic telangiectasia, shear stress stimulates type I/II serine/threonine kinase receptor (ALKs) on the endothelial cell surface and regulates interaction between the receptor and bone morphogenetic proteins 9 and 10 (BMP9 and BMP10)." (PMID 35599845, 2022).
atrial fibrillation (7 papers, 2011 to 2026). A disorder characterized by an electrocardiographic finding of a supraventricular arrhythmia characterized by the replacement of consistent P waves by rapid oscillations or fibrillatory waves that vary in size, shape and timing and are accompanied by an irregular ventricular response. "ANGPT2 is primarily considered a vascular and angiogenic marker, whereas BMP10 is highly cardiac-specific, especially related to atrial tissue and atrial fibrillation risk." (PMID 40823165, 2025). "Along this line, our group recently provided the first evidence of an additional value of BMP10 to NT-proBNP risk stratification in predicting all-cause death and major adverse cardiovascular events in patients with atrial fibrillation." (PMID 39297942, 2025). "BMP10, an emerging biomarker for atrial remodeling and stress, is particularly relevant in conditions like atrial fibrillation, and mitral valve regurgitation." (PMID 40823165, 2025). "Building on genomic and experimental findings, low PITX2 in left atrial cardiomyocytes and high BMP10 in plasma predict recurrent atrial fibrillation in patients after ablation." (PMID 32814717, 2020). "Elevated BMP10 blood concentrations predict atrial fibrillation (AF), AF recurrence after ablation, and AF-related cardiovascular complications like stroke." (PMID 41090224, 2025).
heart failure (7 papers, 2020 to 2025). Inability of the heart to pump blood at an adequate rate to meet tissue metabolic requirements. "Ventricular EHT expresses BMP receptors, and exposure to BMP10 leads to TGFβ-related gene expression associated with AF and heart failure." (PMID 41090224, 2025). "BMP10 exposure induces transcriptomic changes linked to AF and heart failure in ventricular EHT." (PMID 41090224, 2025). "Interestingly though, ALK1, BMP9/BMP10 and endoglin knockout in adult mice similarly result in high-output heart failure, as does Bmp10 deficiency in zebrafish." (PMID 37264878, 2023). "BMP10 released by atrial EHT activates BMP signaling in cardiac fibroblasts, and high BMP10 concentrations induce AF- and heart failure-related transcript networks in ventricular EHT." (PMID 41090224, 2025). "BMP10 induced upregulation of TGFβ pathway transcripts, increased expression of genes related to AF and heart failure, including PITX2 and NPPB, and increased relative contraction times in ventricular EHTs." (PMID 41090224, 2025). "Although animal studies have shown that BMP10 might have a protective function in mice with heart failure, the precise working mechanism of BMP10 remains unclear." (PMID 40496590, 2025). "Consistent with prolonged BMP10 exposure upregulating NPPB, a key gene expressed in ventricular hypertrophy and heart failure, elevated BMP10 concentrations have also been found in heart failure, probably including patients with concomitant AF and heart failure." (PMID 41090224, 2025). "Further research into the effects of BMP10 on cardiac function and its potential contribution to atrial cardiomyopathy, to arrhythmia-induced cardiomyopathy, and to the vicious twins of AF and heart failure is warranted." (PMID 41090224, 2025). "Importantly, unlike markers such as N-terminal pro–B-type natriuretic peptide (NTproBNP), plasma concentrations of BMP10 appear relatively unaffected by other cardiovascular conditions such as heart failure." (PMID 32814717, 2020). "However, combining the biomarkers identified here (BMP10, ANGPT2, FGF23) yielded larger improvements than NTproBNP in this cohort with known heart failure status." (PMID 37798357, 2023). "Furthermore, although the mice with a single knockout of Bmp9 or Bmp10 displayed no obvious phenotypes, the mice with a double knockout of Bmp9 and Bmp10 resulted in vascular defects and high-output heart failure as well as pulmonary hemosiderosis." (PMID 36673052, 2023).
breast cancer (5 papers, 2013 to 2025). A primary or metastatic malignant neoplasm involving the breast. "Dominant negative BMPRII expression in autochthonous mammary cancer mouse model promotes development of metastasis, and loss of BMP10 correlates with disease progression in human patients." (PMID 23967299, 2013). "We next addressed whether the loss of both BMP9 and BMP10 within the same mice would have a more pronounced effect on the E0771 mammary cancer model." (PMID 30165893, 2018). "Herein, we studied the respective roles of BMP9 and BMP10 in tumor growth, tumor angiogenesis and metastatic dissemination using the murine syngeneic orthotopic mammary cancer model (E0771)." (PMID 30165893, 2018). "On the other hand, Bmp10, which has been shown to decrease aggressiveness of breast cancer cells, was downregulated in HFD-E tumors." (PMID 24156623, 2013). "On the other hand, loss of BMP10 did not seem to affect the E0771 mammary cancer model and the double deletion of BMP9 and BMP10 did not lead to a stronger phenotype than the single deletion of BMP9." (PMID 30165893, 2018). "We next addressed the role of BMP10, the other ALK1’s ligand, in the E0771 mammary cancer model." (PMID 30165893, 2018).
cardiac hypertrophy (5 papers, 2016 to 2025). "Earlier investigations have illustrated that mice overexpressing BMP10 develop cardiac hypertrophy characterised by excessive ventricular trabeculae, while mice deficient in BMP10 exhibit hypoplastic and thin ventricles with minimal ventricular trabeculae." (PMID 39611400, 2024). "Bone morphogenetic protein 10, a cardiac peptide growth factor, plays a specific role in cardiac hypertrophy and is considered an influential target for its treatment." (PMID 38659573, 2024). "Upregulation of BMP10 has been reported in mice with myocardial hypertrophy and excessive trabeculation." (PMID 28407751, 2017). "In adults, BMP10 expression is restricted to the right atrium, though ventricular hypertrophy is accompanied by increased BMP10 expression in a rat hypertension model." (PMID 26631724, 2016). "Therefore, BMP10 in Ross broilers may provide compensatory regulation through counteracting upregulated cell cycle inhibitors to promote cardiac hypertrophy under heat stress." (PMID 28407751, 2017).
Stroke (5 papers, 2021 to 2025). Sudden impairment of blood flow to a part of the brain due to occlusion or rupture of an artery to the brain. "Bone morphogenetic protein 10 (BMP10), a more recently discovered biomarker, has been shown to be associated with AF, AF recurrences, and stroke." (PMID 40496590, 2025). "As human PITX2 variants have been associated with increases in cardioembolic stroke, this CM-to-EndoC BMP10 signaling serves as a proposed mechanism for increased AF-associated inflammation and stroke risk." (PMID 35471998, 2022). "For AF screening, enrichment strategies using circulating biomolecules associated with AF, stroke, and heart failure (BMP10, NT-proBNP, troponin, angiopoietin-2, fibroblast growth factor-23, and others) may be useful." (PMID 38953776, 2024). "Our work suggests that this could be multifactorial susceptibility in which decreased PITX2 and increased BMP10 in the LA generates prothrombotic conditions and stroke risk predisposition." (PMID 35471998, 2022). "However, those patients were more severely ill than those in the present study (47% had HF and 12% a history of stroke; NT-proBNP approximately double), and absolute concentrations of BMP10 were only slightly higher." (PMID 34798808, 2021).
Cirrhosis (4 papers, 2020 to 2024). A chronic disorder of the liver in which liver tissue becomes scarred and is partially replaced by regenerative nodules and fibrotic tissue resulting in loss of liver function. "Reduced levels of circulating BMP10 and BMP9, along with elevated levels of endoglin, have been associated with disease severity, decompensation, and pulmonary vascular syndromes in patients with cirrhosis." (PMID 39199400, 2024). "Additionally, studies have shown decreased levels of both BMP9 and BMP10 in plasma samples and liver specimens from patients with decompensated cirrhosis, including those with hepatopulmonary syndrome (HPS) or PoPH." (PMID 39199400, 2024). "Conversely, serum levels of both BMP9 and BMP10 were decreased in patients with cirrhosis compared to patients with pre-cirrhotic liver fibrosis, being associated with disease severity; and a decreased concentration of circulating BMP9 was observed in patients with NAFLD." (PMID 37106416, 2023). "Our hypothesis was that changes in plasma apelin levels would positively correlate with the known reduction of BMP9 and BMP10 in cirrhosis." (PMID 33171278, 2021). "The pulmonary complications of cirrhosis, PoPH and HPS, are associated with markedly reduced BMP9 and BMP10 and increased sEng levels, suggesting that supplementation with exogenous ligands might be a therapeutic approach for PoPH and HPS." (PMID 32454407, 2020). "Plasma BMP9 and BMP10 levels were normal in patients with compensated cirrhosis or fibrosis without cirrhosis, but markedly reduced in patients with decompensated cirrhosis, including those with hepatopulmonary syndrome (HPS) or portopulmonary hypertension (PoPH)." (PMID 32454407, 2020). "Moreover, our findings suggest that supplementation with exogenous BMP9 or BMP10 might be a therapeutic strategy in decompensated cirrhosis and in PoPH and HPS, conditions with a major unmet need." (PMID 32454407, 2020). "In cirrhosis, we identified that plasma BMP9 and BMP10 were reduced and sEng was increased, with the measured levels correlating to disease severity scores." (PMID 32454407, 2020). "However, it is not known whether reductions in BMP9 and/or BMP10, with associated reduction in BMPR-II signalling, correlate with altered levels of apelin in patients with liver fibrosis and cirrhosis." (PMID 33171278, 2021).
dilated cardiomyopathy (3 papers, 2021 to 2023). Cardiomyopathy which is characterized by dilation and contractile dysfunction of the left and right ventricles. "TCAP partially regulates prohypertrophic BMP10, thereby pathogenic variants in the BMP10 gene deter binding to TCAP and increase dilated cardiomyopathy occurrence." (PMID 37752589, 2023). "Studies show that lncRNA Novlnc6 is dramatically down-regulated in dilated cardiomyopathy, and Novlnc6 knockdown leads to the expression decreasing of BMP10 and Nkx2.5, which are two important regulators for cardiomyocytes maturation and differentiation." (PMID 34485393, 2021).
fibrosis (3 papers, 2020 to 2025). the formation of excess fibrous connective tissue in an organ or tissue in a reparative or reactive process. "However, unlike adult TazPM♂, juvenile TazPM♂ hearts do not yet have any detectable cardiac fibrosis, elevated Nppa/Bmp10, or abnormal periostin or lipid deposition evident." (PMID 39125771, 2024).
hepatocellular carcinoma (3 papers, 2023 to 2026). A malignant tumor that arises from hepatocytes. "Similar to the effects of METTL3 deficiency, BMP10 knockdown also promoted hepatoma cell growth, whereas recombinant BMP10 (rBMP10) inhibited it." (PMID 42030359, 2026). "Low levels of BMP10 were found to be associated with bigger tumor size, worse TNM stage, earlier recurrence, and poorer survival in hepatocellular carcinoma." (PMID 37887568, 2023).
Hypertension (3 papers, 2016 to 2025). The presence of chronic increased pressure in the systemic arterial system. "Of note, in adult ventricular cardiomyocytes, the expression of BMP10 is elevated in response to hypertension, indicating that BMP10 is involved in postnatal cardiac physiology." (PMID 36673052, 2023). "Findings of hypertension were observed with overexpression of BMP10 in endothelial cell." (PMID 40720495, 2025). "However, increased BMP10 expression was observed in the hypertrophied ventricles in a rat model of hypertension." (PMID 26631724, 2016).
myeloma (3 papers, 2022 to 2023). "Both BMP9 and BMP10 induce growth arrest and/or apoptosis in multiple myeloma cells in a SMAD1/5/8-dependent manner." (PMID 37095146, 2023). "These cells responded poorly to the ligands BMP2, BMP4 and BMP10, that normally would require ALK3 to signal in myeloma cells." (PMID 36717825, 2023). "Most surprisingly we identified here a switch in ligand specificity as BMP2, BMP4, and BMP10, ligands that usually signal via ALK3 in myeloma cells, gained the ability to signal via ALK2 in the presence of FK506." (PMID 36717825, 2023). "Ligands that typically signal via ALK3 in myeloma cells, BMP2, BMP4, and BMP10, did not induce apoptosis in cells lacking ALK3." (PMID 36717825, 2023).
atherosclerosis (2 papers, 2017 to 2025). A disease characterized by the build-up of fatty material and calcium deposition in the arterial wall resulting in partial or complete occlusion of the arterial lumen. "Because BMP9 and BMP10 are potent mediators of endothelial function it is likely that they also contribute to the pathobiology of vascular diseases such as atherosclerosis." (PMID 28646109, 2017). "Similarly, BMP-4, BMP-10, and BMP-7 have been implicated in cardiovascular physiology and pathology, including vascular inflammation, atherosclerosis, and calcification; however, their prognostic value for systemic cardiovascular risk in patients with PAD has not been established." (PMID 40710778, 2025). "Our findings also show that BMP9 and BMP10 synergize with TNFα to induce expression of BMP2, which is a known regulator of endothelial inflammation and plays a role in atherosclerosis." (PMID 28646109, 2017). "However, the role played by BMP9 and BMP10 in monocyte transmigration across the endothelium, one of the initiating steps in atherosclerosis, has not been studied." (PMID 28646109, 2017).